SNORA70E (small nucleolar RNA, H/ACA box 70E)
Synonyms: U70E
Gene: Small nucleolar RNA gene on chromosome 11 (83,041,464 to 83,041,598, reverse strand). Ensembl gene ENSG00000207221.
Gene Ontology:
Biological process: RNA processing
Cellular component: nucleolus
Homologues: Orthologues: chimpanzee SNORA70 (97% identical), macaque SNORA70 (92% identical). Paralogues in human: SNORA70 (90% identical), SNORA70H (90% identical), SNORA70J (89% identical), SNORA70 (88% identical), SNORA70G (88% identical), SNORA70 (87% identical), SNORA70B (86% identical), SNORA70C (86% identical), SNORA70I (86% identical), SNORA70 (84% identical), SNORA70D (84% identical), SNORA70 (83% identical), and 12 more.